IRF5 (interferon regulatory factor 5)
Diseases named in the same sentence as IRF5 in open-access papers (continued):
Sharing a sentence is not in itself a finding about the gene and the disease.
tumor (continued). "Thus, questions remain regarding the function of IRF5 in the primary tumor microenvironment, the PMN, and the metastatic site." (PMID 38969706, 2024). "Nevertheless, functional t-dEV differences from IRF5-high and -low tumors were established in two distinctly different tumor types, providing the necessary support for focusing on IRF5-mediated immune protection and targeting immune escape at distant sites via loss of IRF5 expression/function." (PMID 38969706, 2024). "We next evaluated whether t-dEVs isolated from IRF5-high or -low tumor cells differentially traffic to organs." (PMID 38969706, 2024). "In conclusion, our findings show that IRF5 expression in tumor cells translates to the packaging of IRF5 mRNA in EVs, causing downstream effects of reduced metastatic burden and immune programming towards a more protective or anti-tumorigenic immune microenvironment." (PMID 38969706, 2024). "The presence of IRF5, though, pulls myeloid cells and macrophages away from a tumor promoting state, releasing inflammatory cytokines, and regulating T cell activation and tumor killing." (PMID 38969706, 2024). "Moreover, IRF-5 acts as a tumor suppressor and is critical for the induction of apoptosis in response to DNA damage in tumor cells." (PMID 37227774, 2023). "IRF5 is a marker of M1 macrophages and plays the role of regulating tumor infiltration." (PMID 32528869, 2020). "We further validated two of the in silico predicted binding partners, CCND2 and IRF5 (tumor-suppressors), and empirically demonstrated their functional roles which might countermeasure FBXL8, in cancer cells." (PMID 32784654, 2020). "Although initially discovered as a key regulator of the type I interferon and pro-inflammatory cytokine arm of the innate immune response, IRF5 has now been found to also mediate pathways involved in cell growth and differentiation, apoptosis, metabolic homeostasis and tumor suppression." (PMID 32582209, 2020). "Indeed, iron oxide nanoparticles have been shown to modulate the IRF-5 (interferon regulatory factor 5) signaling pathway to enhance anti-tumor M1 macrophage polarization while at the same time down-regulate M2-assoicated arginase-1." (PMID 31824960, 2019). "Phenotypic, functional, and gene expression studies reveal a dramatically reduced density of M2-like macrophages in tumor lesions of IRF5/IKKβ NP-treated mice compared to controls, along with increased numbers of inflammatory myeloid cells with distinct M1-type transcriptional profiles." (PMID 31481662, 2019). "On the contrary, IRF5 also acts as a tumor suppressor in several human cancers." (PMID 31681610, 2019). "However, combining radiotherapy as the standard-of-care with IRF5/IKKβ NP injections substantially reduced tumor growth and more than doubled the survival of treated mice compared to the PBS control group (52 days versus 25 days, respectively)." (PMID 31481662, 2019). "In fact, the role of IRF5 in tumor genesis remains controversial." (PMID 28562332, 2017). "Constitutive activation of IRF5 has been identified as indispensable for triggering M-CSF production and the resultant monocyte infiltration and differentiation of M2-type macrophages in tumor tissues." (PMID 28562332, 2017). "IRF5 could also regulate induction of multiple pro-inflammatory cytokines, and then shaped the network of tumor immune microenvironment." (PMID 28562332, 2017). "As such, these data support a Dectin-1 signal-dependent IRF5 activation by tumor cells." (PMID 25149452, 2014). "Our results indicate that NK cells are required to orchestrate with DCs and macrophages for cell killing, wherein activation of the IRF5 transcription factor by Dectin-1 signaling instigated by receptor recognition of N-glycan structures on tumor cells is critical." (PMID 25149452, 2014). "IRF5 is critical for antiviral immunity and functions as a tumour suppresser." (PMID 23028731, 2012).
tumor (continued). "The induction of B-Raf expression detected in thyroid cells transduced with IRF5 could partially explain its tumor-promoting effects." (PMID 22507190, 2012). "The initial observation that the IRF5 protein is not expressed in normal thyrocytes but is detected in neoplastic thyroid cells is somewhat surprising as IRF5 has been usually associated with tumor-suppressor rather than tumor-promoting activities." (PMID 22507190, 2012). "Recent data from irf5-/- mice support its candidacy as a tumor suppressor gene." (PMID 22053985, 2011). "As expected, all samples examined were negative for IRF5 expression, except one that showed very low levels, supporting a correlation between loss of IRF5 expression and tumor metastases." (PMID 22053985, 2011). "The focus of the present study was to examine and compare IRF1 and IRF5 expression in human breast tissue and to determine whether IRF5 acts as a tumor suppressor." (PMID 22053985, 2011). "IRF-5, likely a tumor suppressor, is highly expressed in EBV transformed cells and, together with IRF-4, may be involved in the EBV-mediated regulation of Toll-like receptor 7 activities." (PMID 20209099, 2010). "Besides affecting cytokines to modulate the tumor microenvironment, nanoparticles carrying mRNAs for interferon regulatory 5 (IRF5) and its activating kinase IKKβ were shown to induce M1 polarization of immunosuppressive tumor-associated macrophages and promote tumor regression." (PMID 37805495, 2023). "As an adaptor for TLR7-9 signaling, the TASL-SLC15A4 complex specifically activates the transcription factor IRF5, which in turn induced the release of proinflammatory cytokines, chemokines, and IFNs, the latter of which can play an integral role in tumorigenesis and tumor progression." (PMID 37296415, 2023). "One interesting finding in all IRF5 NP-treated animals was multifocal dense clusters of lymphocytes present within or surrounding the neoplasms, indicating that genetic programming of immune-stimulatory macrophages may restore lymphocyte migration and infiltration into solid tumors." (PMID 31481662, 2019). "Although IRF5 is primarily known as a transcriptional immune regulator, our lab and others have shown that it is also a critical regulator of DNA damage-induced apoptosis and expression of IRF5 is lost in a variety of cancers supporting an important tumor suppressor role for IRF5." (PMID 25649192, 2015). "Since IRF5 is known to be activated by TLRs and other classes of PRRs, we asked whether any of these PRRs is involved in this process in the context of NK cell-mediated control of tumor cells." (PMID 25149452, 2014). "Mechanistically, TOPK suppressed IRF5 expression and HI-TOPK-032 restored CD8+ T cell cytotoxicity in vitro and, with anti-PD-1, further inhibited tumor growth and increased intratumoral cytokine production." (PMID 41868885, 2026). "This work clarifies GDF15’s critical function in fibroblast–tumor cell interactions in 3 key ways: First, GDF15 promotes the growth and invasion of HNSCC cells by up-regulating PCLAF expression via IRF5." (PMID 41035818, 2025). "Nuclear fraction analysis further demonstrated that IRF5 predominantly localized to the nucleus in HNSCC tumor tissues compared to normal controls, and GDF15 overexpression enhanced this nuclear enrichment, whereas GDF15 knockdown reduced nuclear IRF5 levels." (PMID 41035818, 2025). "The most clinically important genes identified using the random forest method were IRF5 and BMI1; we focused on IRF5, as BMI1 was extensively studied in various tumours." (PMID 39993973, 2025). "Violin plots demonstrated significantly elevated activities of IRF5, IRF8, KLF2, TFAP2B, and MAFK in Zbp1−/− tumor cells, while E2F4 and ETV4 were preferentially activated in WT tumors." (PMID 41430036, 2025). "IRF5 is already highly expressed in dendritic cells and is required for TNF release, which enhances tumor cell killing." (PMID 38969706, 2024).
tumor (continued). "Both the M1‐exos and IRF5 M1‐exos groups exhibited significantly suppressed tumor growth rates compared to the PBS group, with the smallest tumor size observed in the IRF5 M1‐exos group." (PMID 39623605, 2024). "In these tumors, it was found that plexin-C1 expression is regulated by interferon regulatory factor-5 (IRF5) and that the expression is highly correlated with the presence of M2 macrophages which promote tumor progression." (PMID 37627074, 2023). "We also found that IRF1, IRF3, IRF4, IRF5 and IRF7 were significantly higher in tumor stage III/IV or grade 3/4 compared with tumor stage I/II or grade 1/2, whereas the expression level of IRF6 was lower in tumor stage III/IV or grade 3/4." (PMID 37182129, 2023). "These released nanoparticles upregulated IRF5 expression and downregulated CCL5 expression in tumor tissues, which led to an increase in M1 phenotype macrophages." (PMID 39574564, 2023). "FBXL8 was found to interact with two tumour suppressors, cyclin D2 (CCND2) and interferon regulatory factor 5 (IRF5)." (PMID 36855778, 2023). "The mRNA levels of INOS, TNF-α, IRF5, IL-10, TGM2, and Arg-1 in the blood of tumor-bearing mice treated with the exosomes were detected by qRT-PCR." (PMID 35600340, 2022). "Interferon regulatory factor-5 (IRF5) is a transcription factor and has essential cellular mechanisms as a tumor suppressor gene." (PMID 35410350, 2022). "Intraperitoneal administration of IRF5/IKKβ mRNA‐PbAE nanoformulation increased T cell infiltration into solid ID8 ovarian cancer, thereby substantially reducing tumor growth." (PMID 36257824, 2022). "More recently, GM-CSF was shown to drive anti-tumor CD4+ and CD8+ T cell immune responses by activating IRF-5 in eosinophils in the tumor microenvironment." (PMID 35865534, 2022). "Especially in the tumor tissue of LUAD, both IRF5 and NOS2 show significant correlations with LPAR6 expression and PTGS2 shows a significant correlation with LPAR6 expression in the tumor tissue." (PMID 34769557, 2021). "Another study demonstrated that CXCL13, which is regulated by interferon regulatory factor 5 (IRF5), mediates CXCR5+ B cells and T cells homing to tumors, thereby eliciting an anti-tumor immune response." (PMID 34947813, 2021). "Co-IP study suggests that two tumor-suppressors, CCND2 and IRF5 are part of the immune-complex of FBXL8." (PMID 32784654, 2020). "Dectin-1 recognizes N-glycan structures from tumor cells, such as in B16 lineage, and activates IRF5 (interferon regulatory factor 5) pathway, among others, to activate natural killer cells to effectively eliminate neoplastic cells." (PMID 32547964, 2020). "FBXL8 was found to interact with two tumor-suppressors, CCND2 (cyclin D2) and IRF5 (interferon regulatory factor 5)." (PMID 32784654, 2020). "In a somewhat reciprocal manner, CSCs isolated from chemoresistant MDA-MB-231-derived cells express interferon regulatory factor 5 (IRF5) and M-CSF, which polarize macrophages to an M2 phenotype and help them acquire tumor-promoting features." (PMID 33371274, 2020). "Among the coding genes within the MDR, IRF5, an essential transcriptional factor activated by TLR signalling, is critical for antiviral immunity and functions as a tumour suppressor." (PMID 23028731, 2012). "The anti-apoptotic effects of NF-kB are balanced in cancer by the tumor suppressor effects of IRF-1 and/or IRF-5 which directly inhibit its cyto-protective activity." (PMID 21569348, 2011). "It was found that it regulated cellular responses along with apoptotic mechanisms in cells without developing resistance in suppressing tumor growth by making changes on Atf2, Casp8, Bcl2 and Irf5 genes and proteins." (PMID 41656578, 2026). "The hydrogel up-regulates IRF5 and down-regulates CCL5 secretion, which contributes to a significant increase in M1 phenotype macrophages, enhancing T-cell-mediated immunity and controlling tumor growth." (PMID 40420798, 2025).
tumor (continued). "These evidences illustrate that IRF1, IRF4, IRF5, IRF6, and IRF8 may be candidate tumor-suppressors in CRC." (PMID 39384770, 2024). "In addition, the inhibition of IRF4, IRF5, IRF7, and IRF8 decreases the survival of PC patients, indicating these IRFs probably act as anti-tumor factors in PC." (PMID 39384770, 2024). "Focusing on CD11b+ myeloid cells revealed minor differences at the later stages of tumor growth in the BC model, but no other major differences between IRF5-high and IRF5-low at any timepoint." (PMID 38969706, 2024). "Nanoparticles formulated with mRNAs encoding the transcription factor interferon regulatory factor 5 (IRF5) and its activating kinase, inhibitor of NF-B kinase subunit-β (IKKβ), reversed the immunosuppressive TME and reprogrammed TAMs, regressing tumours in mouse cancer models." (PMID 37965573, 2023). "Through this pathway, PAMPs binding to TLRs can induce a shift in phenotype; macrophages are suggested to detect viral genetic elements by TLR9, OV-infected tumour cells by TLR2, activating IRF5 which, via the MYD88-IRF5 complex, upregulates NF-κB, IRF5, and IRF7." (PMID 34452439, 2021). "As in the case of CXCL9, IRF5 (interferon regulatory factor 5) can bind to the promoter of CXCL13 and directly regulate its expression in mammary epithelial tumor cells leading to the infiltration of CD19+CXCR5+ B-cell and CD4+CXCR5+ T-cell to the tumor." (PMID 33304345, 2020). "In the absence of T cells, macrophage-programming IRF5/IKKβ NPs still induced 28.4% (±SE/3.5%; n = 5) of the anti-tumor activity observed in the presence of T cells." (PMID 31481662, 2019). "Moreover, our in vivo results were consistent with the findings in vitro, confirming the suppressive effects of SS on HCC HepG2 tumor growth and regulations of CCAT1, miR-375-3p, SP1, and IRF5 expressions." (PMID 31681610, 2019). "As expected for a therapeutic approach that does not directly target or lyse tumor cells, IRF5/IKKβ programming of macrophages delayed tumor progression but did not eradicate the disease in the majority of treated animals." (PMID 31481662, 2019). "In this model, IRF5 tumor suppression is likely mediated through induction of apoptosis, as cells lacking IRF5 are resistant to apoptosis compared to IRF5-expressing cells." (PMID 29438328, 2018). "For the purpose of this review, we will not be discussing the role of IRF5 in cancer as it tends to act as a tumor suppressor and thus its expression/activation are downregulated." (PMID 30515152, 2018). "In immortalized tumor cell lines and primary samples from patients with hematological malignancies, IRF5 expression is always absent or significantly decreased." (PMID 28562332, 2017). "Additional experiments are necessary to determine the exact expression and function of IRF5 in tumor versus non-tumor MECs, stromal cells and non-MECs." (PMID 22053985, 2011). "IRF-5 is a key player of TLR7/TLR9 signalling and is involved in tumor cell growth and apoptosis." (PMID 19430534, 2009). "The co-delivery of IRF5 mRNA and CCL5 siRNA allows for the upregulation of IRF5 and downregulation of CCL5, which can help contribute to a significant increase in M1 phenotype macrophages, which can help reduce tumor growth as M1 macrophages can initiate T cell-mediated immune responses." (PMID 37587290, 2024). "However, our group is also interested in testing whether combinations of IRFs (e.g., IRF5 and IRF8) can synergistically improve the anti-tumor potential we describe here." (PMID 31481662, 2019). "IRF5 expression is absent or significantly decreased in immortalized tumor cell lines and primary samples from patients with hematological malignancies, suggesting for the first time its role as a tumor suppressor gene." (PMID 22053985, 2011).
tumor (continued). "While our findings show that EVs from IRF5-high and -low tumor cell lines differ in function and effect on the PMN, the differences in metastatic potential associated with these t-dEVs may not be entirely related to IRF5." (PMID 38969706, 2024). "Thus, EVs carrying IRF5 may activate the local microenvironment to be more “anti-tumor” whereas the lack of IRF5 creates a “pro-tumor” microenvironment with increased MDSCs, TAMs, and inhibition of activated T cells." (PMID 38969706, 2024). "In addition, it is not known whether the IRF5 genotype of the tumor or some other cell type, such as an immune cell, is where the genotype is relevant to the immune-responsiveness phenotype." (PMID 22909381, 2012).